AGT (angiotensinogen)
Diseases named in the same sentence as AGT in open-access papers (continued):
Sharing a sentence is not in itself a finding about the gene and the disease.
cardiovascular diseases (387 papers, 2007 to 2026). "Genetic studies have linked AGT gene variants, including the M235T genetic variant, to cardiovascular diseases, making it a pertinent target for investigation in the context of ARBs response." (PMID 40248396, 2025). "In vivo studies with mice showed that a dietary supplement consisting of selected botanicals, chlorogenic acid and inulin reduced the risk factors of cardiovascular diseases by lowering hepatic angiotensinogen and angiotensin-II levels, among other factors." (PMID 35631766, 2022). "Angiotensinogen (AGT) and aldosterone play key roles in the regulation of blood pressure and are implicated in the pathogenesis of cardiovascular diseases." (PMID 33925539, 2021). "The results of a genome-wide association study (GWAS) showed that two functional single-nucleotide polymorphisms (SNPs; rs699A>G and rs5050T>G) in the angiotensinogen (AGT) gene were related to cardiovascular disease susceptibility." (PMID 30719178, 2019). "Research has particularly focused on the AGT gene for its association with cardiovascular diseases." (PMID 40248396, 2025). "Several miRNAs influence AGT expression and are associated with cardiovascular diseases." (PMID 39125667, 2024). "Several miRNAs influence AGT and cause cardiovascular diseases." (PMID 39125667, 2024). "Due to its trafficking function, the GOSR2 gene could be associated with the cardiovascular diseases which are highly associated with macromolecules such as insulin, leptin, and angiotensinogen." (PMID 29137253, 2017). "Hence, the findings of associations for both coding and non-coding AGT variants with cardiovascular disease traits implicate various mechanisms possibly involving both protein functional changes and gene regulatory processes in CAD pathways." (PMID 23497386, 2013). "AGT is related to cardiovascular diseases, and the expression of AGT can be adjusted by the Rho-associated protein kinase pathway." (PMID 35455468, 2022). "We next selected several cardiovascular disease-associated factors, including ET-1, and RAS constituents, such as renin, AGT, Ang II, AT1, and AT2, as these factors have been reported to be related to HF." (PMID 28362327, 2017). "Single nucleotide polymorphisms (SNPs) of RAS genes such as angiotensinogen (AGT), angiotensin-converting enzyme (ACE), and angiotensin II type 1 receptor (AT1R) are known to be associated with cardiovascular diseases." (PMID 25961019, 2015). "A large body of literature has established a panel of traditional candidate genes implicated in cardiovascular disease, such as angiotensin-converting enzyme (ACE) and angiotensinogen (AGT)." (PMID 24341666, 2013). "The concentrations of most of these proteins were higher in users, including those that are established biomarkers of cardiovascular disease risk, such as CRP and angiotensinogen." (PMID 22984625, 2012). "Polymorphisms in the genes encoding angiotensinogen (AGT), angiotensin-II converting enzyme (ACE), and angiotensin II type 1 receptor (AT1R) have been extensively studied in cardiovascular diseases, including LVH." (PMID 20594303, 2010). "Contributions of AGT SNPs to cardiovascular diseases have been widely accepted in recent years." (PMID 36836041, 2023). "As the only enzyme known to cleave angiotensinogen and the rate-limiting enzyme of the renin-angiotensin system, plasma renin can increase the synthesis of angiotensin II and aldosterone, which plays a critical role in cardiovascular disease." (PMID 37383707, 2023). "Angiotensinogen (AGT) (encoded by the AGT gene located on chromosome 1q42.2) and ACE play an important role in regulating blood pressure, whereas AGTR1 plays a major role in the etiology of many cardiovascular diseases (CVD)." (PMID 35743896, 2022).
cardiovascular diseases (continued). "The findings reported here for antihypertensive treatment effects of seven AGT SNPs in 2253 CHD cases and 1728 HF cases suggest that a patient's AGT variants might help predict which hypertensive medication(s) can lower cardiovascular disease risk." (PMID 25278896, 2014). "Factors such as angiotensinogen, adiponectin, leptin, angiotensin-converting enzyme and plasminogen activator inhibitor-1 (PAI-1) are all secreted from adipose tissue and have been implicated in the development of cardiovascular disease in the offspring." (PMID 22194901, 2011). "In addition to proteins well known to be related to the risk of mortality and cardiovascular disease (e.g., CRP, adiponectin, angiotensinogen, and prothrombin), a variety are involved in inflammation, as well as others related via as of yet unknown mechanisms." (PMID 29399943, 2018).
tumor (255 papers, 1978 to 2026). "Further analysis revealed that APOD, STC1, F2R, and AGT genes are mainly expressed in tumor-associated fibroblasts." (PMID 40677704, 2025). "AGT has similarly been implicated in tumor growth in various cancers, and our findings further support its role in PC." (PMID 40564071, 2025). "Next, to gain more insights into the association between chemotherapy efficacy and AGT, we detected the proliferation and tumor growth of GC cells with Sh-AGT and/or treated with 5-fluorouracil." (PMID 36986671, 2023). "As tumor-generated angiotensinogen is indicative of splenic HSPCs retention, the angiotensinogen level in human patients is associated with clinical prognosis and has reference value." (PMID 37415162, 2023). "In that retrospective study, the low expression of AGT in the tumor tissue was associated with a prolonged PFS and OS in recurrent GBM patients treated with BVZ." (PMID 30383794, 2018). "AGT promoter methylation status, which we previously identified as a predictive biomarker for bevacizumab response, was analysed in the four cases with primary diagnostic tumour tissues." (PMID 40668315, 2025). "Moreover, tumor tissues obtained from patients with high-risk scores tended to express high level of prognostic genes (AGT, SERPINH1 and MMP7)." (PMID 34215253, 2021). "Angiotensinogen (AGT) promoter methylation status was analysed in all primary tumour samples, while bulk RNA sequencing and TSO500 assays were conducted on all available samples." (PMID 40668315, 2025). "In a transgenic mouse model of hepatocellular carcinoma, the overexpression of human AGT decreased angiogenesis and delayed tumor progression." (PMID 36986671, 2023). "The average tumor volume of HGC-27 cells stably transfected with Sh-AGT was significantly smaller than tumors in the control group." (PMID 36986671, 2023). "Following this, a series of in vitro and in vivo experiments were conducted to evaluate the potential role of AGT in tumor proliferation and migration and the efficacy of chemotherapy." (PMID 36986671, 2023). "Overexpression of angiotensinogen reduces angiogenesis and tumor growth in a hepatocellular carcinoma mouse model and reduces breast cancer proliferation and metastasis." (PMID 33513805, 2021). "The protease renin catalyses the cleavage of angiotensinogen to angiotensin I. Its precursor protein prorenin mediates intracellular processes in tumour cells by activating the WNT/beta-catenin-pathway, which is deregulated in many solid cancers." (PMID 33231730, 2021). "AGT promoter methylation levels of the four CpG sites investigated in tumor tissue from the training cohort showed a significant and high degree of intercorrelation (P < 0.0001 for all possible combinations)." (PMID 32133779, 2020). "Most importantly, ectopic introduction of AGT almost completely abrogated pro-tumor effects of high glucose." (PMID 31142626, 2019). "Consistent with previously reported tumor suppressor function, here we showed that ectopic overexpression of AGT in MCF-7 cells significantly suppressed cell proliferation, anchorage-independent colony formation, migration, and invasion." (PMID 31142626, 2019). "The inhibition of AGT expression significantly decreased AngII levels in the supernatant of these cultured tumor cells under both normoxic and hypoxic condition." (PMID 30208943, 2018). "More importantly, 4T1 mouse tumors with AGT expression silencing made a previously unresponsive control tumor, growing on other site of the mouse, achieve a dramatic response to checkpoint antagonists." (PMID 30208943, 2018). "AGT-silencing didn't significantly inhibit tumor growth of 4T1 (A) and CT26 cells (B) in NOD/SCID mice." (PMID 30208943, 2018). "AngII signal blockage or AGT expression silencing in tumor cells destroys the tumor immunosuppressive microenvironment and improves the tumor response to immune checkpoint inhibitors." (PMID 30208943, 2018).
tumor (continued). "The inhibition of AGT expression greatly decreased Ang II levels in the supernatant of the hypoxic-cultured tumor cells." (PMID 28205588, 2017). "Transcriptomic profile analysis showed that two genes (L1CAM and FBN1) were upregulated and that four genes (AUST2, MAPT, AGT and USH1C) and two microRNAs (hsa-mir-100 and hsa-mir-378) were downregulated, all of which were associated with tumor malignancy." (PMID 29215599, 2017). "Stable suppression of AGT expression in CNE2 tumor cells by RNA interference (RNAi) greatly attenuated HIF-1α accumulation in the pimonidazole-positive hypoxic regions of the xenografted tumors formed in nude mice." (PMID 28205588, 2017). "The bitransgenic mice overexpressing AGT had longer survival time, reduction of tumour growth and blood flow velocities in the liver compared with the hepatocellular model." (PMID 25428203, 2014). "The bitransgenic mice demonstrated reduced angiogenesis, impaired expression of endothelial arterial markers and decreased arterial vessel density, thereby providing evidence that AGT displays anti-angiogenic tumor properties." (PMID 25428203, 2014). "The angiogenic and tumor growth effects of human AGT were further investigated in vivo in a transgenic mouse model." (PMID 25428203, 2014). "The IPA network links AGT to the transcription ofJAG, another factor known to have context-dependent effectson tumour development." (PMID 21479216, 2011). "The overexpression of human AGT decreases angiogenesis and prevents tumor sinusoids from remodeling and arterialization, thus delaying tumor progression in vivo." (PMID 20830311, 2010). "Resistance in tumor cells that are deficient in MMR is unrelated to the level of AGT and is, therefore, unaffected by AGT inhibitors." (PMID 19384285, 2009). "AGT is released in the tumour pseudocyst in vivo in humans, and ACE is expressed by tumour-associated vasculature, suggesting a potential production of all RAS components in the tumour environment." (PMID 14997208, 2004). "Among the traits characteristic of this small patient cohort, primary tumour tissues exhibited methylation levels of the AGT promoter that ranged from 16 to 49%, which is above our previously identified and validated cut point of 12% associated with response to BevCT." (PMID 40668315, 2025). "Moreover, pharmacological inhibition of AChR or Src by treatment with methyllycaconitine (MLA) or dasatinib, respectively, significantly suppressed the NNK-induced tumor multiplicity and load in mice, along with decreases in the expression of pSrc and AGT." (PMID 37258578, 2023). "Additionally, mice with lung-specific overexpression of Src exhibited AGT expression and tumor development in the lung, while heterozygous Agt knockout significantly suppressed Src-mediated lung tumor development." (PMID 37258578, 2023). "Targeting AGT has been widely used to suppress tumor proliferation, migration, and invasion." (PMID 36986671, 2023). "However, AGT, which is attributed to tumor proliferation and migration, as well as invasion, has been demonstrated to be a diagnostic and prognostic biomarker in colorectal carcinoma." (PMID 36986671, 2023). "Similarly, lower expression of AGT in tumor tissues than normal tissues was observed in BRCA, COAD, and LUAD." (PMID 34671200, 2021). "Double immunohistochemical staining on two of the mHNcSCC tissue samples showed expression of angiotensinogen by the SOX2+ CSCs within the tumor nests (TNs), and immunofluorescence showed expression of PRR and AT2R by the SOX2+ CSCs within the TNs and the peritumoral stroma (PTS)." (PMID 33513805, 2021). "The higher expression of AGT in COAD suggested that MALAT1 might promote tumor development through AGT." (PMID 34671200, 2021). "Interestingly, ACE2 and AGT were substantially expressed in tumor tissues compared to normal counterparts in cancers with high expression, such as KIRP, COAD and READ." (PMID 34671200, 2021).
tumor (continued). "Angiotensinogen gene expression is upregulated in tumor samples compared to normal lung tissues." (PMID 33231730, 2021). "Treatment with WFA significantly reduced relative transcript levels of angiotensinogen in tumor samples collected from mice (WFA 2 mg/kg: 0.3676 ± 0.252 fold change; WFA 4 mg/kg: 0.0694 ± 0.144 fold change compared to 1.0081 ± 0.144 fold change in the vehicle-treated group, p < 0.0001)." (PMID 32722688, 2020). "In addition, we measured the relative transcript levels of angiotensinogen in tumors from the tumor-bearing mice." (PMID 32722688, 2020). "Furthermore, the mode-of-action of AGT played as tumor suppressor in the context of high glucose is still to be defined." (PMID 31142626, 2019). "Most notably, exogenously introduced AGT almost completely abrogated the high glucose-elicited pro-proliferative and pro-metastatic effects on MCF-7 cells, which indicated that the pro-tumor properties of high glucose were heavily depended on suppression of AGT expression." (PMID 31142626, 2019). "Therefore, an attractive opportunity to examine in upcoming studies is the full molecular characterization of the tumor tissue, to analyze the interaction between the expression of AGT rs5050 in blood and these biomarkers currently used." (PMID 30383794, 2018). "Interestingly, silencing AGT expression in 4T1 cells achieved a long-term tumor remission in all of the mice treated with PD-1 checkpoint inhibitor and induced a relapse-free survival." (PMID 30208943, 2018). "Furthermore, AGT expression suppression in tumor cells had the same impact on tumor infiltrating T cells as the candesartan treatment." (PMID 30208943, 2018). "Furthermore, an AngII signaling blockage reversed the tumor immunosuppressive microenvironment, and inhibition of angiotensinogen (AGT, a precursor of AngII) expression strongly triggered an immune-activating cytokine profile in hypoxic mouse cancer cells." (PMID 30208943, 2018). "Interestingly, Ang II was markedly attenuated in pimonidazole-positive regions of the tumors formed by AGT-inhibited tumor cells." (PMID 28205588, 2017). "Furthermore, AGT-silencing similarly resulted in reduced expression of HIF-1α protein in hypoxic tumor cells." (PMID 28205588, 2017). "AGT, O6-alkylguanine-DNA alkyltransferase, is an important DNA repair protein and many studies have reported that hypoxia can inhibit DNA repair to promote tumor malignancy and genetic instability." (PMID 29215599, 2017). "Moreover, in our model, Angiotensinogen (AGT) was produced by the tumor and their receptor (AGTR1) was located in membrane from adjacent tissue." (PMID 24597571, 2014). "However, in the liver surrounding CRC metastases treatment with captopril resulted in significantly lower angiotensinogen mRNA expression at almost all time points compared to both the sham and control tumor-induced liver (P ≤ 0.0160)." (PMID 20380732, 2010). "AGT is involved in the suppression of tumor growth and metastasis." (PMID 20830311, 2010). "We are also testing novel [99mTc]Tc-AGT-7 analogues for an increased tumor homing capacity and evaluating dual magnetic resonance imaging (MRI)/fluorescent AGT-7 analogues that could be utilized also for fluorescent-guided surgery, providing real-time intraoperative feedback." (PMID 40872566, 2025). "Consequently, DNA methylation levels of the AGT promoter could be reduced during tumor progression as a result of hypoxia/necrosis, inflammation, or long‐lasting corticosteroid dependency." (PMID 32133779, 2020). "Therefore, the altered immune microenvironment in a local tumor by AGT expression-silencing may elicit an in situ tumor vaccination and generate productive tumor-specific T cells to achieve a systemic in vivo anti-tumor effect." (PMID 30208943, 2018).